ANXA6 (annexin A6)
Diseases named in the same sentence as ANXA6 in open-access papers (continued):
Sharing a sentence is not in itself a finding about the gene and the disease.
cancer (continued). "Hence, differential expression patterns of AnxA6 expression levels and its interaction partners will likely result in cell-specific intra- and extracellular scaffolding functions, contributing differently to the progression and treatment outcome of the various cancers." (PMID 35806209, 2022). "In summary, apigenin modulates the mineralization process by regulating AnxA6 and TNAP, as well as through various effects on normal and cancer bone tissues or atherosclerotic soft tissue." (PMID 36361965, 2022). "We investigated the protein expression of ANXA6 and EGFR in cancer tissue from 81 patients with TNBC." (PMID 34238922, 2021). "Compared with the normal group, GCA, ANXA6, and BIRC5 in the cancer group were increased." (PMID 40616392, 2025). "Moreover, AnxA6 up- or downregulation impacted on the efficacy of tyrosine kinase inhibitors to inhibit growth, migration and invasion of EGFR-related cancer cells." (PMID 33810523, 2021). "However, given the paradoxical quiescent metabolic phenotype following AnxA6-downregulation in TNBC cells, metabolic phenotyping of certain cancer cells in vitro should be interpreted with caution due to the rapid depletion of the limiting lipid supply in the culture media." (PMID 35267416, 2022). "Moreover, the underlying mechanisms were uncovered, and we evidenced that ANXA6-exo up-regulated YAP1 to promote Hippo pathway dysregulation, and the promoting effects of ANXA6-exo on PTX resistance and cancer aggressiveness in BC cells were abrogated by silencing YAP1." (PMID 34676207, 2021). "Overexpression of ANXA6 and accumulation of cholesterol in LEs could reduce cholesterol-sensitive cell mass formation, fibronectin (FN) secretion, and integrin recycling, and thereby reducing LDL-induced migration and invasion of hamster ovarian cells, and A431 cancer cells." (PMID 37129645, 2023). "Whether the overall mode of action of ANXA4 (membrane curvature) and ANXA6 (membrane constriction) is similar in cancer and skeletal muscle cells or not, the mechanism would be slightly different, with an ANXA4-induced inward versus outward curvature, respectively." (PMID 35207075, 2022). "However, studies performed in cancer cells have shown that ANXA4 accumulated at the damaged area, where it may induce invagination of the membrane wound, in order to facilitate the constriction of the hole by ANXA6." (PMID 35207075, 2022). "While the biochemical mechanism of AnxA6 inactivating phosphorylation of EGFR and ERK1/2 is not completely explored in cancer cells." (PMID 37528485, 2023). "Notably, MCF7A4−CRISPR cells appeared to compensate from lack of ANXA4 by upregulating their ANXA6 protein expression, suggesting that MCF7 cancer cells require at least one of these proteins to counteract plasma membrane damage." (PMID 29158488, 2017).
epithelial carcinoma (8 papers, 2013 to 2023). "Overexpression of AnxA6 in human squamous A431 epithelial carcinoma cells is associated with decreased migration in wound healing, as well as reduced invasion in matrigel and organotypic matrices." (PMID 32784650, 2020). "In human squamous A431 epithelial carcinoma cells, which overexpress EGFR but lack endogenous AnxA6, stable expression of AnxA6 was associated with reduced cell growth." (PMID 32784650, 2020). "Consequently, like NPC1 deficiency, elevated AnxA6 levels reduced cholesterol-sensitive caveolae formation, FN secretion and integrin recycling, effectively reducing LDL-inducible migration and the invasion of CHO and A431 carcinoma cells." (PMID 35806209, 2022). "In EGFR overexpressing A431 epithelial carcinoma lacking endogenous AnxA6, restoration of AnxA6 expression promoted PKCα-mediated threonine 654-EGFR phosphorylation, which inhibited EGFR tyrosine kinase activity, cell growth, migration and invasion." (PMID 33810523, 2021). "Furthermore, elevated AnxA6 scaffold levels contributed to improving the efficacy of tyrosine kinase inhibitors (TKIs) targeting EGFR to reduce growth, migration, and invasive properties of EGFR overexpressing A431 carcinoma cells." (PMID 35806209, 2022). "Since mitochondria have a critical role in shaping Ca2+ signals we examined mitochondrial morphology and function in primary ear fibroblasts from AnxA6−/− mice and control littermates, and A431 epithelial carcinoma cells (since this cell line does not express anxA6)." (PMID 23341998, 2013).
infection (8 papers, 2018 to 2025). The state of being infected such as from the introduction of a foreign agent such as serum, vaccine, antigenic substance or organism. "In particular, an increased expression of ANXA6 is observed soon after HL-mEC infection, which declines over time concomitantly to the enhanced expression of MX1." (PMID 34361874, 2021). "The significantly impaired number of NP-positive nuclei seen during infection of AnxA6-overexpressing A431 cells as well as A549 cells indicated that early IAV infection was affected." (PMID 30042202, 2018). "Co-expression of a myc-tagged ANXA6 and viral M2, followed by infection provided evidence of a direct interaction between the two molecules." (PMID 30498445, 2018). "While ANXA6's role in membrane repair and exocytosis may initially mitigate epithelial damage, we speculate that sustained expression during infection likely perpetuates inflammation by maintaining EspF activity." (PMID 41522448, 2025). "In summary, in NPC1-inhibited A549 cells, through either AnxA6 expression or U18666A treatment, the cholesterol imbalance in the LE/L compartment restricted the first infection cycle of incoming IAV particles, independently of the antiviral properties of IFITM3." (PMID 30042202, 2018). "Notably, several members from Annexin A family (ANXA1, ANXA2, ANXA4, ANXA5 and ANXA6) were overrepresented in DEVs from Lm-infected BMDCs but remained unaltered in total cell lysates, suggesting a specific sorting during infection of these ANXA family members to EVs." (PMID 36131943, 2022). "In line with the notion that enhanced LE/L cholesterol negatively affects IAV early infection, the proportion of infected cells strongly increased (62.0% ± 4.62%) when NPC1 was transiently coexpressed together with AnxA6 in these cells." (PMID 30042202, 2018).
head and neck neoplasm (1 paper, 2020). A benign or malignant neoplasm that affects the anatomic structures of the head and neck region. "In addition, it will be of great benefit to expand the research on ANXA6 to head and neck neoplasms as a potential therapeutic target for radiosensitization in the future." (PMID 32373608, 2020).
heart disease (1 paper, 2022). "The observation that annexin A6 localizes to the site of cardiomyocyte injury, forming a repair cap at the membrane lesion, supports a role for annexin A6 in heart disease associated with increased cellular breakdown." (PMID 35866481, 2022).
myopathy (1 paper, 2021). A disease of the muscle in which the muscle fibers do not function properly. "In this transparent and powerful model organism for the study of vertebrate biology, AnxA6 and other annexins accumulated at the site of muscle damage, with AnxA6 deficiency leading to myopathy." (PMID 33810523, 2021).
ANXA6 also shares sentences with these, for which no sentence is quoted: esophageal adenocarcinoma (4 papers); chronic myeloid leukaemia (2); large cell lymphoma (2); acute myeloid leukaemia (1); Anxiety (1); Arthritis (1); atherosclerosis (1); atopic dermatitis (1); benign prostate hyperplasia (1); breast (1); breast adenocarcinoma (1); calcific aortic valve disease (1); calcification (1); cervical intraepithelial neoplasia (1); coronary artery disease (1); dilated cardiomyopathy (1); dysferlinopathy (1); End stage renal disease (1); gastroenteritis (1); glioblastoma multiforme (1); glioma (1); head and neck cancer (1); head and neck squamous cell carcinoma (1); Hypercalcemia (1); infectious disease (1); Insulin resistance (1); invasive ductal carcinomas (1); laryngeal carcinoma (1); lung squamous cell carcinoma (1); mesothelioma (1).
A further 10 diseases each share a sentence with ANXA6 in 1 paper.